OR1A1 (olfactory receptor family 1 subfamily A member 1)
Description:
Odorant receptor.
Synonyms: OR17-7
Tractability: Small molecule: it belongs to a druggable protein family. Antibody: its Gene Ontology location is reachable by antibodies, with high confidence; UniProt places it where antibodies can reach, with medium confidence; UniProt predicts a signal peptide or a membrane-spanning region.
Gene: Protein-coding gene on chromosome 17 (3,207,539 to 3,218,896, forward strand). Ensembl gene ENSG00000172146.
Subcellular location: Cell membrane
Pathways (Reactome):
Sensory Perception: Expression and translocation of olfactory receptors; Olfactory Signaling Pathway
Gene Ontology:
Molecular function: G protein-coupled olfactory receptor activity; olfactory receptor activity; G protein-coupled receptor activity
Biological process: adenylate cyclase-activating G protein-coupled receptor signaling pathway; detection of chemical stimulus involved in sensory perception of smell; signal transduction; G protein-coupled receptor signaling pathway
Cellular component: plasma membrane; membrane
Genetic constraint (gnomAD): Loss-of-function variants: 8 observed, 12.14 expected, observed/expected ratio (o/e) 0.66, 90% interval 0.39 to 1.19. The upper end of that interval is the gene's LOEUF score, 1.19, which puts it in group 5 of 6, group 1 being the genes least tolerant of losing a copy. Missense variants: 391 observed, 400.25 expected, observed/expected ratio (o/e) 0.98, 90% interval 0.9 to 1.06. Synonymous variants: 145 observed, 155.29 expected, observed/expected ratio (o/e) 0.93, 90% interval 0.81 to 1.07.
Homologues: Orthologues: chimpanzee OR1A1 (99% identical), macaque OR1A1 (94% identical), dog OR1A1 (87% identical), mouse Or1a1 (84% identical), mouse Or1a1b (84% identical), rat Or1a1b (82% identical), rat Or1a1 (81% identical). Paralogues in human: OR1A2 (83% identical), OR1F1 (52% identical), OR1E1 (52% identical), OR1J2 (52% identical), OR1L4 (52% identical), OR1L6 (51% identical), OR1N1 (51% identical), OR1J4 (51% identical), OR1K1 (51% identical), OR1L1 (51% identical), OR1E2 (50% identical), OR1M1 (50% identical), and 116 more.
Diseases named in the same sentence as OR1A1 in open-access papers:
OR1A1 is named in the same sentence as 3 diseases in open-access papers, as found by Europe PMC text mining. Sharing a sentence is not in itself a finding about the gene and the disease. The quoted sentences say what the papers report.
cancer (2 papers, 2019 to 2025). A tumor composed of atypical neoplastic, often pleomorphic cells that invade other tissues. "In our study, we selected six human olfactory receptors including OR51E2, OR52cs, TAAR9, OR51E1, OR1A1, and OR1A2 that have been linked with research for the possible development of cancer treatment and detection methods." (PMID 39944883, 2025).
tumor (2 papers, 2020 to 2021). "In recent research, human olfactory receptor 1A1 (OR1A1) activation was observed in 11 different tumor types by the analysis of single-cell transcriptomes." (PMID 34218656, 2021). "For example, OR8B8 and OR8H1 were exclusively detected in malignant breast epithelial cells, whereas OR1A1 and OR2M3 activation were observed in 11 and 10 different tumor types respectively, suggesting a distinct mode of expression regulation." (PMID 32917933, 2020).
OR1A1 also shares sentences with these, for which no sentence is quoted: colorectal cancer (1 paper).